EDA (ectodysplasin A)
Description:
Cytokine which is involved in epithelial-mesenchymal signaling during morphogenesis of ectodermal organs. Functions as a ligand activating the DEATH-domain containing receptors EDAR and EDA2R. May also play a role in cell adhesion (By similarity). [Isoform 1]: Binds only to the receptor EDAR, while isoform 3 binds exclusively to the receptor EDA2R. [Isoform 3]: Binds only to the receptor EDA2R.
Synonyms: ED1; EDA2; EDA1; XLHED; HED; XHED; ED1-A1; ED1-A2; EDA-A1; EDA-A2; ECTD1; HED1; ODT1; STHAGX1; TNLG7C
Tractability: Small molecule: it has a binding pocket of medium quality. Antibody: UniProt places it where antibodies can reach, with high confidence; its Gene Ontology location is reachable by antibodies, with high confidence; UniProt predicts a signal peptide or a membrane-spanning region.
Gene: Protein-coding gene on chromosome X (69,616,067 to 70,039,472, forward strand). Ensembl gene ENSG00000158813.
Subcellular location: Cell membrane; Secreted (Ectodysplasin-A, secreted form)
Subcellular location (Human Protein Atlas): Vesicles; Lipid droplets; Predicted to be secreted
Pathways (Reactome):
Immune System: TNFs bind their physiological receptors
Gene Ontology:
Molecular function: cytokine activity; protein binding; signaling receptor binding; tumor necrosis factor receptor binding
Biological process: cytokine-mediated signaling pathway; odontogenesis of dentin-containing tooth; positive regulation of canonical NF-kappaB signal transduction; immune response; odontogenesis; cell communication; regulation of non-canonical NF-kappaB signal transduction; signaling
Cellular component: extracellular region; cytoskeleton; membrane; plasma membrane
Homologues: Orthologues: chimpanzee EDA (100% identical), macaque EDA (98% identical), rat Eda (95% identical), mouse Eda (95% identical), rabbit EDA (94% identical), pig EDA (92% identical), dog EDA (91% identical), guinea pig EDA (91% identical), tropical clawed frog eda (65% identical), zebrafish eda (50% identical). Paralogues in human: COL11A1 (34% identical), COL5A1 (34% identical), COL11A2 (32% identical), COL2A1 (28% identical), COL5A3 (28% identical), COL1A1 (27% identical), COL5A2 (26% identical), COL3A1 (26% identical), COL1A2 (25% identical), COL4A5 (24% identical), COL4A2 (24% identical), COL24A1 (24% identical), and 25 more.
Diseases named in the same sentence as EDA in open-access papers:
EDA is named in the same sentence as 117 diseases in open-access papers, as found by Europe PMC text mining. Sharing a sentence is not in itself a finding about the gene and the disease. The quoted sentences say what the papers report.
hypohidrotic ectodermal dysplasia (46 papers, 2008 to 2026). A genetic disorder of ectoderm development characterized by malformation of ectodermal structures such as skin, hair, teeth and sweat glands. "The corresponding missense variant in the human EDA gene, p.Ala349Thr, has been reported as a recurring pathogenic variant in several human patients with X-linked hypohidrotic ectodermal dysplasia." (PMID 39062633, 2024). "Deficiency of ectodysplasin A1 (EDA1) due to variants of the gene EDA causes X-linked hypohidrotic ectodermal dysplasia (XLHED), a rare genetic condition characterized by abnormal development of ectodermal structures." (PMID 35923710, 2022). "Mutations in the EDA gene mapped at Xq13.1 showed an X-linked hypohidrotic ectodermal dysplasia (HED), a rare disease characterized by hypoplasia or absence of sweat glands, dry skin, sparse hair, and pronounced oligodontia." (PMID 35707781, 2022). "EDA is a unique gene involved in the pathogenesis of X-linked hypohidrotic ectodermal dysplasia (XLHED; OMIM 305100), which accounts for 95% of patients with HED, and the remaining 5% are mainly due to autosomal dominant or recessive inheritance." (PMID 35873474, 2022). "X-linked hypohidrotic ectodermal dysplasia with the cardinal symptoms hypodontia, hypotrichosis and hypohidrosis is caused by a genetic deficiency of ectodysplasin A1 (EDA1)." (PMID 34456978, 2021). "Hypohidrotic ectodermal dysplasia (HED) is a group of genodermatoses in which deficient ectodysplasin A signalling leads to maldevelopment of skin appendages, various eccrine glands, and teeth." (PMID 34479575, 2021). "This represents the first form of X-linked hypohidrotic ectodermal dysplasia in cattle that affected both EDA and AWAT2 genes." (PMID 33801223, 2021). "A mutation in the epithelial morphogen gene ectodysplasin-A1 (EDA1) is responsible for the disorder X-linked hypohidrotic ectodermal dysplasia (XLHED), the most common form of ectodermal dysplasia." (PMID 32176048, 2020). "X-linked hypohidrotic ectodermal dysplasia (XLHED) is caused by pathogenic variants of the gene EDA disrupting the prenatal development of ectodermal derivatives." (PMID 31924237, 2020). "The molecular basis of X-linked hypohidrotic ectodermal dysplasia (XLHED) involves disruption in EDA protein." (PMID 31452656, 2019). "X-linked hypohidrotic ectodermal dysplasia (XLHED) caused by variants in the EDA gene represents the most common ectodermal dysplasia in humans." (PMID 27449516, 2016). "Hypohidrotic ectodermal dysplasia (HED) is an X-linked trait caused by hypomorphic mutation in the IKBKG (or EDA) gene, encoding nuclear factor κB essential modulator (NEMO)." (PMID 26239454, 2015). "The EDA gene has been reported responsible for X-linked hypohidrotic ectodermal dysplasia (XLHED) in humans characterized by impaired development of hair, eccrine sweat glands, and teeth." (PMID 18545687, 2008). "Mutations in ectodysplasin A have been previously identified as the cause of X-linked hypohidrotic ectodermal dysplasia (XLHED) (OMIM 305100)." (PMID 18545687, 2008). "In addition, FoxO1 induced the expression of ectodysplasin A (Eda) and its receptor Eda2r, which are known to be associated with X-linked hypohidrotic ectodermal dysplasia and are involved in salivary gland development in myoepithelial cells." (PMID 38212454, 2024). "Pathogenic variants of the gene EDA cause X-linked hypohidrotic ectodermal dysplasia (XLHED), a hereditary disease characterized by defective development of ectodermal appendages and a symptomatic triad consisting of hypotrichosis, oligo- or anodontia, and hypo- or anhidrosis." (PMID 36293046, 2022). "Similarly, EDA is the only gene known to be associated with X‐linked hypohidrotic ectodermal dysplasia, which accounts for 95% of cases of hypohidrotic ectodermal dysplasia (HED)." (PMID 33943035, 2021). "EDA is involved in X-linked ‘hypohidrotic ectodermal dysplasia’ (HED)." (PMID 28877219, 2017).
hypohidrotic ectodermal dysplasia (continued). "Mutations in the ectodysplasin A (EDA) gene are associated with X‐linked hypohidrotic ectodermal dysplasia (HED), a genetic disorder characterised by abnormalities in the formation of skin, hair, nails, teeth and sweat glands." (PMID 41185962, 2025). "Most of the mutations in EDA are identified to cause X-linked hypohidrotic ectodermal dysplasia (HED)." (PMID 36982827, 2023). "Hypohidrotic ectodermal dysplasia (HED) characterised by developmental defects of sweat glands, hair and teeth, is caused by ectodysplasin-A (EDA) gene mutation, indicating that EDA signals play indispensable roles in the development of sweat glands." (PMID 32014004, 2020). "Background/Objectives: X-linked hypohidrotic ectodermal dysplasia (XLHED) is a rare monogenic disorder characterized by hypohidrosis, hypotrichosis, and hypodontia, caused primarily by pathogenic variants in the EDA gene." (PMID 41465157, 2025). "One of the most well-characterized forms is hypohidrotic ectodermal dysplasia (HED), typically caused by variants in EDA (ectodysplasin A), EDAR (ectodysplasin A receptor), or EDARADD (EDAR-associated via death domain), and is defined by hypohidrosis, oligodontia with conical teeth, and sparse hair." (PMID 40428341, 2025). "X-linked hypohidrotic ectodermal dysplasia (XLHED), caused by a genetic deficiency of ectodysplasin A1 (EDA1), is a rare developmental disorder of ectodermal derivatives such as hair, sweat glands, and teeth." (PMID 37108325, 2023). "Mutations in any of EDA, EDAR, and EDARADD can contribute to hypohidrotic ectodermal dysplasia (HED), which affects 1 in 10,000–100,000 newborns." (PMID 34938205, 2021). "Patients with mutations in the ectodysplasin receptor signalling pathway genes – the X-linked ligand ectodysplasin-A (EDA), the receptor EDAR or the receptor adapter EDARADD – have hypohidrotic ectodermal dysplasia (HED)." (PMID 31028034, 2019). "Human patients with hypohidrotic ectodermal dysplasia (HED) have developmental defects in teeth, hair and salivary glands caused by mutations in EDA, EDAR or EDARADD." (PMID 27590203, 2016). "This analysis helps shed light on the nasal gland defects observed in patients with hypohidrotic ectodermal dysplasia (HED) (defect EDA pathway) and LADD syndrome (defect FGFR2b pathway)." (PMID 27590203, 2016). "Hypohidrotic ectodermal dysplasia (HED) represents one of the major types of EDs and is due to mutations in the EDA (MIM *300451), EDAR (MIM *604095) and EDARADD (MIM *606603) genes." (PMID 25662550, 2015). "EDA (ectodysplasin A) encodes a protein (TNF-Ligand protein) involved in X-linked hypohidrotic ectodermal dysplasia, characterized by sparse hair, lack of sweat glands, and microdontia." (PMID 40995403, 2025). "In X-linked hypohidrotic ectodermal dysplasia (XLHED), the genetic deficiency of the signaling molecule ectodysplasin A1 (EDA1) may even be overcome before birth by administration of a recombinant replacement protein." (PMID 36147498, 2022). "X-linked hypohidrotic ectodermal dysplasia (XLHED; #MIM 305100), a rare hereditary disease characterized by missing or dysplastic skin appendages and teeth, is caused by deficiency of the signaling protein ectodysplasin A1 (EDA1) during early development." (PMID 34456978, 2021). "X-linked hypohidrotic ectodermal dysplasia (XLHED) is the most common subtype, with an incidence of 1/50,000–100,000 males, and is associated with the EDA gene (Xq12-q13.1); the dominant and recessive subtypes involve the EDAR (2q13) and EDARADD (1q42.3) genes, respectively." (PMID 31796081, 2019). "Hypohidrotic ectodermal dysplasia (HED, OMIM 224900) is a rare autosomal recessive syndrome resulting from germline mutations in any of the EDA, EDAR or EDARADD genes in humans." (PMID 36699680, 2022). "In humans, mutations in the genes encoding EDA, EDAR, or the cytosolic signal mediator EDARADD cause a condition known as hypohidrotic ectodermal dysplasia (HED)." (PMID 26581094, 2015).
hypohidrotic ectodermal dysplasia (continued). "This is not an unbroken ground, as prenatal therapy was recently shown to correct X-linked hypohidrotic ectodermal dysplasia (XLHED), a rare genetic disorder caused by a lack of sweat gland development due to a deficiency in ectodysplasin A (EDA)." (PMID 39423254, 2024).
ectodermal dysplasia (39 papers, 2009 to 2025). "This is the first report of Ectodysplasin A related hypohidrotic ectodermal dysplasia in Limousin cattle and the description of a novel causal variant in cattle." (PMID 38252617, 2024). "Han Y., Wang X., Zheng L., Zhu T., Li Y., Hong J., Xu C., Wang P.,Gao M. Pathogenic EDA mutations in Chinese Han families with hypohidrotic ectodermal dysplasia and genotype-phenotype: a correlationanalysis." (PMID 38023809, 2023). "Chen Y., Molloy S., Thomas L., Gambee J., Bächinger H., Ferguson B.,Zonana J., Thomas G., Morris N. Mutations within a furin consensussequence block proteolytic release of ectodysplasin-A and causeX-linked hypohidrotic ectodermal dysplasia." (PMID 38023809, 2023). "In this patient, we detected a hemizygous pathogenic deletion in EDA, which was causal for the patient ́s hypohidrotic ectodermal dysplasia phenotype." (PMID 35874679, 2022). "Mutations of the Ectodysplasin-A (EDA) gene are generally associated with syndrome hypohidrotic ectodermal dysplasia or nonsyndromic tooth agenesis." (PMID 34545288, 2021). "One study that addresses both aspects is the X-linked anhidrotic-hypohidrotic ectodermal dysplasia mouse (Tabby), harboring an ectodysplasin A (EDA) mutation." (PMID 34499624, 2021). "The X-linked anhidrotic-hypohidrotic ectodermal dysplasia mouse (Tabby) is a naturally developed ectodysplasin A (EDA) mutant mouse strain." (PMID 33233466, 2020). "Such systemic treatment with Ecto-D2 is capable in mouse of inducing an ectodermal dysplasia phenotype that matches that of EDA gene mutation in exposed embryos." (PMID 30789897, 2019). "In conclusion, we provide a phenotypic description of dogs with an ectodermal dysplasia phenotype, and identified an unusual splice defect of the EDA gene, which most likely causes this phenotype." (PMID 27449516, 2016). "In this study, we identified a novel splice defect of the EDA gene as the likely cause of an ectodermal dysplasia in dogs." (PMID 27449516, 2016). "EDA is a well-known gene that causes ectodermal dysplasia; however, several studies also reported that mutations in EDA can cause non-syndromic oligodontia." (PMID 26406231, 2015). "In this study we identified a new mutation in the bovine EDA gene causing ectodermal dysplasia in Holstein Friesian cattle breed." (PMID 21740563, 2011). "Genetic mutations implicated in ectodermal dysplasia commonly involve the ectodysplasin A, ectodysplasin A Receptor, and ectodysplasin A receptor-associated death domain genes, among others, which play essential roles in the ectodysplasin signalling pathway crucial for ectodermal organ development." (PMID 41523862, 2025). "Another CNV of uncertain significance is Xq13.1, which involves EDA gene that is associated with ectodermal dysplasia, a group of abnormalities that might manifest with hearing loss; however, our patient had NSHL with no other complications." (PMID 38378725, 2024). "In hypohidrotic ectodermal dysplasia, protein replacement therapies such as Fc-ectodysplasin A (Fc-EDA) fusion protein help enhance gland and tooth development in prenatal care." (PMID 39022466, 2024). "Bayés M., Hartung A., Ezer S., Pispa J., Thesleff I., Srivastava A.,Kere J. The anhidrotic ectodermal dysplasia gene (EDA) undergoesalternative splicing and encodes ectodysplasin-A with deletion mutationsin collagenous repeats." (PMID 38023809, 2023). "The purpose of this study was to report a new variant in the EDA gene leading to HED and provide an overview of the phenotypic and allelic heterogeneity of EDA-related ectodermal dysplasia in cattle." (PMID 36068608, 2022). "EDA, a member of the TNF superfamily, is one of the functional genes that regulate the development of sweat glands, and mutations in EDA can cause ectodermal dysplasia in humans and lead to sweat-free syndrome." (PMID 29329593, 2018).
ectodermal dysplasia (continued). "The EDA gene represents the primary functional candidate gene for the observed ectodermal dysplasia phenotype, and is located at 54,078,743–54,515,535 bp on the X-chromosome within the shared haplotype on the X-chromosome." (PMID 27449516, 2016). "Genetic testing ruled out mutation of the ectodermal dysplasia-associated genes EDA, EDAR and EDARRAD11." (PMID 28589954, 2017). "Furthermore, the CRISPRa-based enhancement of endogenous ectodermal dysplasia ectodysplasin (EDA) gene expression in keratinocyte cells and their successful reprogramming into sweat gland cells has also been reported, which is an important aspect of wound-healing therapy." (PMID 40650152, 2025). "Four genes (EDA, EDAR, EDARADD, WNT10A) account for 90% of hypoidrotic/anhidrotic ectodermal dysplasia cases." (PMID 34078430, 2021). "Such an ectodermal dysplasia syndrome is reminiscent of similar phenotypes in other vertebrates because of impairments of the EDA receptor (EDAR; a member of the TNF family) or its ligand EDA, indicating a conserved role of this pathway in reptiles as well." (PMID 28439533, 2016).
tooth agenesis (37 papers, 2008 to 2025). A tooth disease characterized by failure to develop one or more missing teeth. "In a clinical study, individuals with EDA pathogenic variants presented variable phenotypes ranging from selective tooth agenesis and syndromic forms." (PMID 40428404, 2025). "Although previous studies have identified more than one hundred mutations related to XLHED in EDA, only a few EDA variants have been implicated in nonsyndromic tooth agenesis." (PMID 34545288, 2021). "Among these genes, PAX9 (paired box gene 9), MSX1 (muscle segment homeobox 1), AXIN2 (axis inhibition protein 2), and EDA (ectodysplasin A) are the most frequently reported genes associated with nonsyndromic hypodontia." (PMID 28401166, 2017). "EDA is an important gene associated with tooth agenesis, it is located on chromosome Xq12–q13.1 and encodes for ectodysplasin-A (EDA) (MIM 300451), a member of the tumor necrosis factor (TNF) family." (PMID 24312213, 2013). "Digenic mutations of both WNT10A and EDA were identified in 2 of 88 (2.27%) isolated oligodontia cases and 4 of 26 (15.38%) syndromic tooth agenesis cases." (PMID 24312213, 2013). "We found that six participants harbored digenic mutations in both WNT10A and EDA: two of them had isolated oligodontia and the others had syndromic tooth agenesis." (PMID 24312213, 2013). "Here we identify novel mutations in the EDA gene that are involved in the X-linked isolated hypodontia and provide an explanation for the clinical phenotype at the molecular structural level." (PMID 18545687, 2008). "EDA variants were present in 86.9% of deciduous tooth agenesis cases, suggesting that EDA is specifically required for deciduous tooth development and its variants are major pathogenic factors for deciduous tooth agenesis." (PMID 39408781, 2024). "Variants in ectodysplasin A (EDA) accounted for 86.9% of patients with deciduous tooth agenesis." (PMID 39408781, 2024). "This study verifies the fact, collected by other authors around the world, that pathogenic variants in WNT10A, EDAR, and EDA are the most frequently known causes of autosomal recessive hypodontia/oligodontia, autosomal recessive HED, X-linked HED, and X-linked isolated tooth agenesis." (PMID 31652981, 2019). "This is the first study to show that simultaneous WNT10A and EDA mutations could lead to tooth agenesis in the Chinese population." (PMID 24312213, 2013). "WNT10A and EDA digenic mutations could result in oligodontia and syndromic tooth agenesis in the Chinese population." (PMID 24312213, 2013). "Therefore, we hypothesized that EDA mutations interact with WNT10A mutations to play a role in tooth agenesis." (PMID 24312213, 2013). "Moreover, EDA mutations are also associated with cases of isolated tooth agenesis." (PMID 24312213, 2013). "The tenth locus for tooth agenesis has been mapped on the X chromosome at Xq13.1 and corresponds to the EDA gene." (PMID 40428404, 2025). "Tooth agenesis is associated with several genes; however, non-syndromic human tooth agenesis has been associated with mutations in AXIN2, EDA, PAX9, MSX1, and PAX9." (PMID 39156431, 2024). "EDA mutations are known to cause two overlapping phenotypes: HED and non-syndromic tooth agenesis (NTA)." (PMID 34573371, 2021). "Causative variants in genes of the EDA/EDAR/NF‐κB pathway, such as EDA and EDARADD, have been widely identified in patients with non‐syndromic tooth agenesis (NSTA)." (PMID 33943035, 2021). "Mutations in several genes have been associated with familial tooth agenesis, among others MSX1, PAX9, AXIN2, EDA, EDARADD, and EDAR." (PMID 33743023, 2021). "Research has identified an association between mutations in MSX1, PAX9, EDA, AXIN2, WNT10A, WNT10B and LRP6 and human tooth agenesis." (PMID 31914153, 2020). "Among several genes involved in tooth development, mutations in MSX1, PAX9, AXIN2, WNT10A, EDA and KDF1 have been reported to play a role in tooth agenesis 6–13." (PMID 33014315, 2020).